CD68 (CD68 molecule)
Diseases named in the same sentence as CD68 in open-access papers (continued):
Sharing a sentence is not in itself a finding about the gene and the disease.
tumor (continued). "Simple immunological analysis of the existing immune response in the cancer tissue, for example, the presence of CD8-positive lymphocytes as well as CD68-positive macrophages, and their localization inside the tumor, could be added into the basic pathomorphological diagnosis of NSCLC patients." (PMID 34502043, 2021). "In addition, as expected, CCL2 staining of the ICs was significantly positively correlated with the presence of different immune cells/cell markers, such as CD3 (T cells), CD8 (T cells), CD68 (macrophages), PD-L1 in TCs and ICs, and the percentage of stromal tumor-infiltrating lymphocytes (sTILs)." (PMID 32429318, 2020). "Future studies should examine whether CSF1/CSF1R acts synergistically with CD4+ Th1 cells to activate anti-tumor CD68+ macrophages, or adaptive CSF1 secretion upon exposure to CD4+ T cell-derived cytokines act detrimentally to recruit M2-like TAMs and consequently hamper antitumor immune responses." (PMID 32850346, 2020). "Interestingly, it has been demonstrated that macrophage subpopulations differently distribute between the invasive front, internal tumor area or adjacent normal mucosa: CD68+ cells are located more in the tumor area, while CD80+ macrophages are highly expressed within the adjacent normal mucosa." (PMID 32650452, 2020). "However, our current observation invites speculation that the increased infiltrating CD68+-TAMs may be M1 dominant, contributing to anti-tumour activity, which will be determined in our future experiments." (PMID 32765828, 2020). "Interestingly, a negative association between the amount of CD68+ TAM infiltrate in total tumor tissue and TNM clinical stage was found, while TAM density within cancer cell area positively correlated with Gleason score." (PMID 33194645, 2020). "Thus, an immune cell composition of CD4+CD68+CSF1R+ could exert strong anti-tumor effects with great cooperativity between these immune factors." (PMID 32850346, 2020). "Our results showing strong positive prognostic significance of stromal CD68+ infiltrate in HGSOC tumours warrants further investigation into the role and properties of CD68+ macrophages in HGSOC and also may caution against the use of new potential macrophage-depleting therapies." (PMID 32249277, 2020). "In the paradigm of full differentiation and polarization by tumor cells alone, our results do not support a clear role for TGFα in polarization, as the primary effect of inhibiting TGFα is the loss of CD68+ macrophages rather than a shift in the percentage of CD163+ macrophages." (PMID 33069212, 2020). "Thus, due to limited size of the tumour sample within the array, we are not able to demonstrate the expression of CD68+-TAMs and the loss of IL-34/M-CSF at the interface of tumour invasion region in the existing immunohistochemically stained slides." (PMID 32765828, 2020). "Thus, it is possible that infiltrating CD68 positive macrophages in some STS could produce factors that have a trophic effect on the tumor cells, and that chemotherapy effects on these macrophages could result in less production of tumor supporting factors." (PMID 30999901, 2019). "Different markers were used to identify TAMs in CRC, and CD68 had been widely recommended as a pan-macrophage marker, making this protein unspecific to the TAMs correlated with tumor growth, which might explain these discrepant effects of TAM subtypes on the EMT regulation of CRC." (PMID 30927925, 2019). "However, the correlation between B7-H3 and CD31 or α-SMA expression was much higher than that of B7-H3 and CD68 expression, suggesting that B7-H3 may play a vital role in the tumor microenvironment, including endothelial cells and fibroblasts." (PMID 31998637, 2019).
tumor (continued). "CD68+ macrophages are innate immune cells that play a broad role in host defense and the maintenance of tissue homeostasis, but some research had shown that increased CD68+ macrophage densities were related to increased tumor progression and worse prognosis in RCC patients." (PMID 31192136, 2019). "To understand the tumor microenvironment of AIPpos tumors, we evaluated expression of several key components of the tumor microenvironment using specific molecular markers for macrophages (CD68), T-reg cells (FOXP3), cytotoxic T cells (CD8), and memory T cells (CD45RO)." (PMID 30867568, 2019). "However, GKT771 or DC101 alone or in combination did not affect the ratio of mature (CD45+/CD11b+/F4-80+) and immature (CD45+/CD11b+/F4-80−) macrophages or the frequency of total–tumor-associated macrophage (TAM) populations (CD45+/CD11b+/CD68+/F4-80+ and CD45+/CD11b+/CD68+/F4-80−)." (PMID 31249132, 2019). "Moreover, we showed a significant correlation between CD68+ macrophage numbers and tumor location." (PMID 29541395, 2018). "Moreover, HPV interacts with CD68+ macrophages by recruiting them to the tumor site." (PMID 29541395, 2018). "Preoperative diagnostic biopsies (n = 26), tumor resection specimens (n = 34), tumor-free lymph nodes (n = 28) and lymph node metastases (n = 10) of T1/T2 oscc patients were immunohistochemically analyzed for Gal3 and macrophage marker (CD68, CD11c, CD163 and MRC1) expression." (PMID 30115022, 2018). "Furthermore, tumor tissues from GDC-0941-treated mice also displayed significantly higher levels of CD68+ staining than those from the vehicle-treated group, suggesting that PI3K inhibition may induce macrophage infiltration." (PMID 30042442, 2018). "As we can see, the treatment of asialyl-agalactosyl IgG did not change an expression of a general macrophage marker CD68 but increased mRNA and protein levels of tumor-associated macrophage markers CD163 and CD204 in both macrophagic U-937 cells and human peripheral macrophages at day six." (PMID 30469416, 2018). "Additionally, the entire tumor core area of the Vehicle-treated GL261-implanted GBM mice showed pronounced expression of CD68 (CD68high/Iba1(−) GBM tumor cells), whereas the scar tissue area of the CCP-treated and rescued mice was devoid of the CD68high (GBM tumor cells) population." (PMID 30041669, 2018). "Since tumor-associated microglia and macrophages are the most abundant population of immune cells found in GBM, we further investigated mutual exclusivity of ZEB1 with CD68 or HLA-DR (as a marker of activated microglia and macrophages) in additional GBM cases (N = 8) using co-labeling." (PMID 28945795, 2017). "However, within this group, it is possible that the effect of relatively high CD8+ T cell infiltration could be modulated due to PD-1 activation on the T cells and its interaction with the PD-L1 ligand expressed by either CD68 or tumour cells in some patients." (PMID 28122336, 2017). "In addition, IL-15 administration reduced the number of infiltrating F4/80+/CD68+ cells in the tumor mass, in line with the hypothesis of a preferential NK-myeloid cell communication mediated by IL-15." (PMID 29286001, 2017). "Another 511 ESCC patients tumor tissues from three different centers including Northern and Southern areas of China (validation sets) were collected to confirm whether CD68 and IL-13 based model had popular prognostic priority in patients from different areas or not." (PMID 26771842, 2016). "Moreover, a high density of CD169+ cells correlated with early clinical stage and no LN metastasis, while a higher CD169+ to CD68+ ratio was significantly associated with small tumor size and a low Ki-67+ rate." (PMID 27861544, 2016).
tumor (continued). "Although few previous studies have shown that the CD68 expressed in tumor cells, our novel findings was supported by Strojnik and coworkers, whose researches confirmed that the cancer cells exhibit expression of CD68 and the high CD68 staining of cancer cells correlated with poor prognosis." (PMID 26769084, 2016). "The necrotic foci were also devoid of CD68+ cells having the morphological features of myeloid cells with scavenger activity, whereas some of the CD68 positivity in the areas surrounding the necrosis was due to the presence of tumour cells, as demonstrated by their STAT6-positive nuclei." (PMID 27304187, 2016). "Both tumors showed negative staining for CD68 as marker for tumor-associated macrophages." (PMID 27112768, 2016). "CD68-positive TAMs and tumor necrosis may prove as valuable tools regarding patient selection." (PMID 26497197, 2015). "We have recently proposed that malignant cells can “express” ectopic immune epitopes, which are typical of immune cells (i.e., CD73, CD68) and that these may serve as tumor antigens to evade immune surveillance facilitating homotypic interactions in distant organs during metastatic process." (PMID 26427914, 2015). "Furthermore, tumor microenvironment galectin-3 was shown to interfere with TAM recruitment, because infiltrating CD68+ cells were observed into the tumor mass, while these cells were only found in the periphery of galectin-3 negative tumors engrafted in KO mice." (PMID 24982845, 2014). "However, CD163 may be a superior marker of TAMs due to its higher specificity, as compared to CD68, for M2 macrophages, which are involved in tumor angiogenesis and progression." (PMID 24489836, 2014). "Increase in CD68 positive macrophages in our study supports the hypothesis that inflammatory macrophages expressing TREM-1 may contribute to continued production of mediators which may promote tumor growth." (PMID 24842612, 2014). "The prognostic effect of post-chemotherapy CD68 infiltration was especially observed in those patients with residual tumor (no pCR), in whom a higher CD68 count trended to associate with worse DFS in univariate (P = 0.055) and multivariate analysis (P = 0.09; HR = 2.26, 95% CI: 0.86 to 5.96)." (PMID 25432519, 2014). "Interestingly, the distribution of macrophages significantly differed: while macrophages were generally equally distributed in the stroma and close to pancreatic ducts in CP, CD68+ macrophages were predominantly located adjacent to the tumor cells in over 50% of PDACs." (PMID 24797069, 2014). "Furthermore, chemotherapy increased the percentage of CD68+ TAMs within the tumor." (PMID 25294815, 2014). "While the TAMs function to antagonize the anti-tumor effect of oncolytic viruses in GBMs, the CD68+ population may clear the apoptotic cancer cells in response to oncolytic treatment, whereas the CD163+ population may promote the growth of the remaining uninfected cancer cells." (PMID 24675569, 2014). "Interestingly, the distribution pattern of the CD68-positive cells was notably different in 0–4 dpi and 6–8 dpi tumors changing from an intra- and peritumoral scattered pattern to a strong accumulation of macrophages at the tumor margin." (PMID 23441176, 2013). "These RT-recruited CD68-positive macrophages may act as M2 macrophages to promote tumor invasion." (PMID 23940516, 2013). "Thus, high CD3, CD20 or CD68 counts were significantly associated with MMP-9 expression, at the invasive front; whereas high CD68 count was significantly associated with MMP-14 and TIMP2 in this same tumor location." (PMID 23300781, 2012). "Since the injected tumor cells are identical in the two types of animals, we hypothesized that Mig is produced from a host-derived cell that invades the tumor, and our colocalization experiment with a macrophage marker, CD68, confirms this." (PMID 19200397, 2009). "However, the spindle cells and the giant cells of such a tumor are usually positive for CD68." (PMID 18081931, 2007).
tumor (continued). "CD68 was used as a marker of TAM infiltration, reflecting changes in immune cell presence within the tumor while PECAM-1 staining was used to assess vessel density and normalization in response to therapy." (PMID 40802092, 2026). "In order to assess the expression of DCN in tumour cells, stroma and immune cells, SPTCs from 27 patients were stained with a 6‐plex immunofluorescent panel including DCN, CD4, CD8, CD20, CD68, and PanCK." (PMID 41392017, 2026). "Mechanistically, knockdown of CD68 in CAFs led to the upregulation of chemokines CCL17 and CCL22 in tumor cells, thereby enhancing Treg cell recruitment." (PMID 40656546, 2025). "Moreover, the immunohistochemical profile of the tumor microenvironment revealed that the expression content of tumor-associated macrophages (CD163, CD68) and fibroblasts (SMA) differs between cancerous and precancerous tissues which may regulate the disease development." (PMID 40416971, 2025). "As expected, given their generally relatively high abundance, αSMA+ fibroblasts, CD68+/CD163- macrophages, and CD31+/CD34+ endothelial cells were near each other, tumor cells, and T cells across all molecular subgroups examined." (PMID 39969434, 2025). "According to our research, regions of tumours with high LOX and LOXL2 levels also had higher expression of CD68 and CD206, which were known to be markers of macrophages and M2 macrophages, respectively." (PMID 40179101, 2025). "Because Akk induces homeostatic immune responses, we evaluated Tumor-Infiltrating Immune Cells, such as CD3+ T cells or CD68+ macrophages, in specimens with PD-L1 low expression (n=30)." (PMID 40990022, 2025). "In our case, CD4, CD68, and CD163 were all positive, and Lysozyme showed a small amount of sporadic positive expression, suggesting that the tumor cells originated from histiocytes." (PMID 40231251, 2025). "Macrophage markers (CD68 and CD163) were immunohistochemically determined in formalin fixed paraffin-embedded slides containing the primary tumor and surrounding adipose tissue." (PMID 40940394, 2025). "In the setting of iCryo, which spares peripheral tumor zones from full necrosis, increased infiltration of CD8+ cytotoxic T lymphocytes and CD68+ macrophages were observed, alongside a reduction in CD206+ M2-like macrophages." (PMID 41377976, 2025). "The expression of PD-L1 and the tumor microenvironment markers (CD4, CD8, CD68, and CD163) were examined in LSCC using immunohistochemistry." (PMID 40429363, 2025). "Composite indices were generated to quantify immune suppression (PD-L1, PD-1, LAG3, FOXP3, IDO, CD68), CAF activation (SMA, Vimentin), endothelial activation (CD31), and tumor proliferation (Ki67)." (PMID 41595458, 2025). "Stroma cell labeling indices of CD4**, CD8*, Foxp3*, CD68*, CD163**, and CD11c* were significantly higher in both the tumor core and the invasive front of cSCC samples as compared to BCC (*p < 0.001; **p < 0.050)." (PMID 41068337, 2025). "In low-grade CMT and ICgI, CD68+ cells are sparse and perivascular, while, in high-grade SC, CSA, ICgIII, and IMC, TAMs are more abundant, frequently infiltrating tumor nests and the surrounding stromal compartments." (PMID 40725175, 2025). "Other studies have reported B7-H3 expression in immune cells within the tumor microenvironment (TME), including CD68-positive macrophages and intratumor neutrophils, as well as in α-SMA-positive fibroblasts." (PMID 40214484, 2025). "We performed immunohistochemical examination of CD4, CD8, CD68, and CD163 subpopulations in tumor sections." (PMID 41256864, 2025). "Immunohistochemical staining identified CD68+ and CD163+ macrophages both within the tumor and in the surrounding stroma." (PMID 41007741, 2025). "In this particular case, the tumor cells expressed CD23, CD15, CD31, CD3, CD35, CD68, and cell cycle protein D1." (PMID 40629639, 2025).
tumor (continued). "M2TAMs are characterized by the expression of CD68 and CD163 and are known to secrete immunosuppressive cytokines (e.g., IL-10, CCL17, CCL22) that promote angiogenesis, matrix remodeling, and tumor cell migration." (PMID 40281554, 2025). "More than 50% of MCs were colocalized with neighbouring cells of the tumour microenvironment within 20 μm, most frequently with monocytes (CD14+CD68+), M2 macrophages (CD68+CD163+), and endothelial cells (CD31+)." (PMID 40981193, 2025). "Multiple immune cell markers were evaluated, including T cell markers, CD3, CD4, CD8; the macrophage marker CD68; CK-SOX10 tumor marker; and immune modulatory factors, PD1, PDL1, FOXP3, IFN-γ, NOS2, and COX2." (PMID 40663402, 2025). "Lastly, an association between cSCC sLI CD4 and T status (p = 0.011), CD11c and N status (p = 0.041), CD68 and infiltrations depth (p = 0.018), as well as CD8 and CD11c and previous tumor (p = 0.006; p = 0.029, respectively) was observed." (PMID 41068337, 2025). "Histological evaluation confirmed the diagnosis of cutaneous histiocytic sarcoma, with tumor cells expressing CD163 and CD68." (PMID 40901224, 2025). "After that, the tumor tissue microarrays were subjected to multi-label immunofluorescence staining of CD28 (yellow), CD68 (green), CD80 (red), and CD8 (orange)." (PMID 40541951, 2025). "IHC results demonstrated significant expression of BCL2A1, CD68, and CD163 within the tumors, with BCL2A1 exhibiting a distribution pattern highly similar to that of CD68 and CD163, primarily localized in the tumor stroma region." (PMID 40707992, 2025). "For each case, the number of CD68- and CD34-positive cells per 1.38 × 105 μm2 were measured at multiple locations in the deepest infiltration zone and tumor center, respectively, and the mean values were calculated." (PMID 40243510, 2025). "CD3+ T cells, CD20+ B lymphocytes, CD68+ macrophages, CD66b+ neutrophils, the nucleus-defining dye DAPI, and tumor cells expressing CD56 and synaptophysin (tumor markers: TM) were stained by multi-parametric fluorescence IHC together in one tissue section." (PMID 40282480, 2025). "Similarly, CD68+ macrophages can be differentiated into M1 and M2 macrophages, with TAMs generally thought to resemble M2‐polarized macrophages, which play a role in promoting tumor cell proliferation and progression as well as inhibiting immune response mediated by T lymphocytes." (PMID 40789673, 2025). "Immunohistochemistry (IHC) staining of patient tumor sections and immunofluorescence (IF) staining of organoid sections for CD99, VIM, CD68, KI67, and SATB2 showed positive expression in both, confirming histopathological similarities." (PMID 40476445, 2025). "The expression profiles of IL1β, IL10, IL18, TNF-α, TLR4, GATA3, and CD68 in HHV-infected PCa FFPE biopsies indicated an inflammatory environment conducive to immune alteration and potential tumour progression." (PMID 40430084, 2025). "Using GeoMx DSP technology, we selected ROIs for each sample, including tumor cells (PanCK+), immune cells (CD45+), and macrophages (CD68+)." (PMID 40467555, 2025). "We performed CD68 immunohistochemistry on FFPE samples from HGSOC patients, which further validated the preferential distribution of macrophages in tumours verses normal adjacent tissue." (PMID 41275425, 2025). "They suggest that tumor-infiltrating M1 (CD86+) and M2 (CSF1-R+) macrophages have a peri-T location and that more macrophages (CD68+) than DLBCL cells (CD20+) express these two markers." (PMID 41415285, 2025). "Panel 3 complements Panels 1 and 2, as it was designed to assess LAG-3 expression on cytotoxic T cells (CD8+LAG-3+), macrophages (CD68+LAG-3+), NK cells (CD56+LAG-3+), Treg cells (FOXP3+LAG-3+) and tumour cells (SYN+LAG-3+)." (PMID 41285059, 2025).